MIR2113 (microRNA 2113)
Synonyms: hsa-mir-2113
Gene: MicroRNA gene on chromosome 6 (98,024,531 to 98,024,621, forward strand). Ensembl gene ENSG00000238367.
Homologues: Orthologues: chimpanzee MIR2113 (100% identical), dog MIR2113 (100% identical), macaque MIR2113 (100% identical), pig MIR2113 (100% identical), rabbit MIR2113 (100% identical).
Diseases named in the same sentence as MIR2113 in open-access papers:
MIR2113 is named in the same sentence as 1 disease in open-access papers, as found by Europe PMC text mining. Sharing a sentence is not in itself a finding about the gene and the disease.
MIR2113 shares sentences with these, for which no sentence is quoted: respiratory diseases (1 paper).